GALNT9 (polypeptide N-acetylgalactosaminyltransferase 9)
Description:
Catalyzes the initial reaction in O-linked oligosaccharide biosynthesis, the transfer of an N-acetyl-D-galactosamine residue to a serine or threonine residue on the protein receptor. Does not glycosylate apomucin or SDC3.
Synonyms: GalNAc-T9; GALNACT9
Tractability: Antibody: UniProt predicts a signal peptide or a membrane-spanning region.
Gene: Protein-coding gene on chromosome 12 (132,196,372 to 132,329,598, reverse strand). Ensembl gene ENSG00000182870.
Subcellular location: Golgi apparatus membrane
Subcellular location (Human Protein Atlas): Vesicles
Pathways (Reactome):
Metabolism of proteins: O-linked glycosylation of mucins
Gene Ontology:
Molecular function: polypeptide N-acetylgalactosaminyltransferase activity
Biological process: protein O-linked glycosylation; protein O-linked glycosylation via N-acetyl-galactosamine
Cellular component: Golgi apparatus; Golgi membrane
Genetic constraint (gnomAD): Loss-of-function variants: 50 observed, 58.47 expected, observed/expected ratio (o/e) 0.86, 90% interval 0.68 to 1.08. The upper end of that interval is the gene's LOEUF score, 1.08, which puts it in group 4 of 6, group 1 being the genes least tolerant of losing a copy. Missense variants: 828 observed, 875.97 expected, observed/expected ratio (o/e) 0.95, 90% interval 0.89 to 1. Synonymous variants: 396 observed, 362.39 expected, observed/expected ratio (o/e) 1.09, 90% interval 1.01 to 1.19.
Homologues: Orthologues: macaque GALNT9 (95% identical), mouse Galnt9 (91% identical), rat Galnt9 (91% identical), pig GALNT9 (91% identical), dog GALNT9 (90% identical), tropical clawed frog galnt9 (88% identical), zebrafish galnt9 (84% identical), chimpanzee GALNT9 (39% identical), guinea pig Galnt9 (36% identical), Caenorhabditis elegans gly-3 (31% identical), Drosophila melanogaster Pgant5 (31% identical), Drosophila melanogaster Pgant7 (30% identical), and 10 more. Paralogues in human: GALNT17 (61% identical), GALNT18 (50% identical), GALNT8 (44% identical), GALNT13 (32% identical), GALNT6 (32% identical), GALNT3 (31% identical), GALNT1 (31% identical), GALNT4 (31% identical), GALNT11 (30% identical), GALNT5 (30% identical), GALNT16 (30% identical), GALNT10 (29% identical), and 7 more.
Diseases named in the same sentence as GALNT9 in open-access papers:
GALNT9 is named in the same sentence as 26 diseases in open-access papers, as found by Europe PMC text mining. Sharing a sentence is not in itself a finding about the gene and the disease. The quoted sentences say what the papers report.
breast carcinoma (7 papers, 2015 to 2025). "Forty-eight hours after initial transfection with siRNA oligos against BNC1, CCDC8 or GALNT9 breast cancer cell lines showed loss of specific gene expression." (PMID 26052355, 2015). "The correlation between Galnt9 and the clinical prognosis of neuroblastoma and serous ovarian cancer has been well‐established, and its association with brain metastasis in breast cancer has also been documented." (PMID 40492591, 2025). "For example, in breast cancer the GALNT9 gene has been found to be hypomethylated in primary tumors while there is a loss of expression through promoter hypermethylation in brain metastases, thus suggesting a role of GALNT9 in the later stages of breast cancer." (PMID 31635093, 2019). "GALNT9 is also located in a CpG island and showed hypermethylation in AN, which was also reported in brain metastasis from primary breast cancer." (PMID 37794510, 2023). "In this study, cfDNA mapped to TRAF3IP3, PTPRN2 and GALNT9 gene loci in hypomethylated regions exhibited substantially increased short fragments ratio in patients with breast cancer." (PMID 37740218, 2023). "For instance, the altered cfDNA fragmentation profile in TRAF3IP3, PTPRN2 and GALNT9 gene loci, along with their upregulated expression could remind us the chromatin changes due to the development of breast carcinomas." (PMID 37740218, 2023). "GALNT9, BNC1 and CCDC8 were knocked down in breast cancer cell lines by siRNA and applied to matrigel-coated invasion chambers as described in the methods." (PMID 26052355, 2015).
neuroblastoma (5 papers, 2014 to 2025). Neuroblastoma (NB) is the most common solid, extracranial childhood tumor. "Loss of GALNT9 expression in neuroblastoma has been linked to a highly malignant phenotype and associated with poor overall and disease free survival." (PMID 26052355, 2015). "GALNT9 was significantly higher expression in high‐grade serous ovarian cancer, and expression of GALNT9 was associated with OS, can be serve as a prognostic marker for personalized therapy of neuroblastoma." (PMID 34894053, 2022). "Although the molecular mechanism involving GALNT9 and other factors in low-risk neuroblastoma patients remain largely unknown, the GALNT9 has been validated as a prognostic marker that may be helpful to guide therapy in low-risk neuroblastoma patients." (PMID 27322213, 2016).
breast tumours (3 papers, 2015 to 2022). "From the panel of four genes selected from our analyses of HumanMethylation 450 K BeadChip arrays obtained from TCGA, only one gene, GALNT9, was frequently methylated (55 %) in metastatic brain tumours originating from primary breast tumours." (PMID 26052355, 2015). "This analysis has identified three genes (BNC1, CCDC8 and GALNT9) that are differentially methylated in primary breast tumours and BBM." (PMID 26052355, 2015). "Pangeni et al42 have found GALNT9 is often epigenetically dysregulated in breast tumours that metastasis to the brain, and may be involved in the progression of primary breast tumours to brain metastases." (PMID 34894053, 2022). "However, conserved mutations have been identified in approximately 2 % of microsatellite instable colorectal cancers and GALNT9 is also mutated, infrequently (<1 %), in astrocytoma and lung tumours and infrequently lost through CNV in breast tumours." (PMID 26052355, 2015). "We have identified three genes, GALNT9, CCDC8 and BNC1, that were frequently methylated (55, 73 and 71 %, respectively) and silenced in BBM and infrequently methylated in primary breast tumours." (PMID 26052355, 2015). "From our broad-ranging screens, we have identified GALNT9, BNC1 and CCDC8 as frequently methylated in BBM and significantly less frequently methylated in primary breast tumours." (PMID 26052355, 2015). "Both early and late methylation events will appear similarly in our initial analysis; the genes will be frequently methylated in BBM and infrequently methylated in unrelated primary breast tumours, this is the case for BNC1, CCDC8 and GALNT9." (PMID 26052355, 2015). "Of these, GALNT9 and BNC1 were infrequently methylated in primary breast tumors, suggesting that they may be metastasis virulence genes and dysregulation of these occur as late events involved in brain colonization of these cancer cells." (PMID 28993799, 2017). "CCDC8 was commonly methylated in brain metastases and their associated primary tumours whereas GALNT9 and BNC1 were methylated and silenced only in brain metastases, but not in the associated primary breast tumours from individual patients." (PMID 26052355, 2015). "Our analysis of such tumour pairs identified that BNC1 and GALNT9 are not frequently methylated in any breast tumours, even those that will eventually develop into brain metastases where these genes are methylated." (PMID 26052355, 2015). "The GALNT9 promoter was methylated in 3/5 brain metastases and not methylated in any of the corresponding primary breast tumours." (PMID 26052355, 2015). "Our findings indicate that epigenetic dysregulation of GALNT9, CCDC8 or BNC1 in breast tumours may contribute to metastasis to the brain and possibly other distant organs." (PMID 26052355, 2015). "GALNT9 and BNC1 promoter methylation and associated silencing is common in BBM but does not occur frequently in the originating breast tumours suggesting that their dysregulation may not necessarily benefit the primary tumour but are required for successful colonization of the brain." (PMID 26052355, 2015). "We found GALNT9 to be frequently methylated in BBM (55 %) and not methylated in any of the 40 primary breast tumours (p = 0.0001)." (PMID 26052355, 2015). "GALNT9 and BNC1 methylation is uncommon in primary breast tumours and is often not detectable in the tumours that metastasise." (PMID 26052355, 2015).
autism (2 papers, 2009 to 2022). Persistent deficits in social interaction and communication and interaction as well as a markedly restricted repertoire of activity and interest as well as repetitive patterns of behavior. "Three genes that encode anabolic enzymes, which are among the 107 DEGGs, have been reported as candidate genes for autism, and they are Large1, Galnt9, and Hs3st5." (PMID 36568890, 2022). "Gene-network analysis of the genes highlighted by Prioritizer in the non-complex-autism group revealed a putative gene-network in four CNVs containing genes known to operate in glycobiology (B3GALT6, GCNT2, LARGE, and GALNT9)." (PMID 19492091, 2009).
pituitary adenoma (2 papers, 2019). "In pituitary adenoma, the methylation alteration of LAMA2, GALNT9 and DAP methylation has been proven to be related to tumor invasion." (PMID 31796052, 2019).
brain tumours (1 paper, 2015). "We analysed the methylation status BNC1, CCDC8 and GALNT9 in metastatic brain tumours and corresponding primary tumours from individual patients." (PMID 26052355, 2015). "Total RNA was extracted from 15 metastatic brain tumours to determine the expression of BNC1, CCDC8 and GALNT9 by RT-PCR." (PMID 26052355, 2015).
corneal diseases (1 paper, 2025). "Two genes (Rgs2 and Galnt9) were involved in pathways related to human corneal diseases, including cGMP-PKG signaling, mucin-type O-glycan biosynthesis, and oxytocin signaling." (PMID 40323269, 2025).
glioma (1 paper, 2023). A benign or malignant brain and spinal cord tumor that arises from glial cells (astrocytes, oligodendrocytes, ependymal cells). "However, EXTL1, ST8SIA3, and GALNT9 demonstrated a negative relation with oncogenic pathways, suggesting a potentially protective role for glioma progression." (PMID 37663248, 2023).
lung adenocarcinoma (1 paper, 2025). A carcinoma that arises from the lung and is characterized by the presence of malignant glandular epithelial cells. "To verify whether these findings in NEPC can be applied to other NE cancers, we examined GALNT9 and O‐GalNAc levels in the lung adenocarcinoma (LUAD) cell line A549 and the small cell lung cancer (SCLC) cell lines NCI‐H146 and NCI‐H82." (PMID 40492591, 2025).
ovarian carcinoma (1 paper, 2023). A malignant neoplasm originating from the surface ovarian epithelium. "On the other hand, the model composed of GALNT9, UPF3A, WARS, and LDB2 incorrectly identified 1 out of 16 cancer cases (6.25%: ovarian cancer)." (PMID 37794510, 2023).
schizophrenia (1 paper, 2024). A major psychotic disorder characterized by abnormalities in the perception or expression of reality. "Another top-hit hypermethylated gene, GALNT9, has been implicated in schizophrenia through glycosylation dysregulation." (PMID 38516266, 2024).
small cell lung carcinoma (1 paper, 2025). Small cell lung cancer (SCLC) is a highly aggressive malignant neoplasm, accounting for 10-15% of lung cancer cases, characterized byrapid growth, and early metastasis. "Inhibition of O‐GalNAc glycosylation or knockdown of Galnt9 demonstrates efficacy in restraining the liver metastasis of NEPC, small cell lung cancer (SCLC), and colorectal neuroendocrine cancer." (PMID 40492591, 2025). "Here, we find that the glycosyltransferase GALNT9 is highly expressed in NEPC, small cell lung cancer (SCLC), and neuroendocrine colon cancers, leading to an increased presence of O‐GalNAc glycosylation on the cell surface." (PMID 40492591, 2025).
cancer (7 papers, 2017 to 2025). A tumor composed of atypical neoplastic, often pleomorphic cells that invade other tissues. "CRHR2, INMT, and GALNT9 expression have been shown to be associated with cancer and may play a role in regulating the self-renewal and proliferation of cancer stem cells." (PMID 40358182, 2025). "Targeting of GALNT9 or O‐GalNAc glycosylation can effectively inhibit the development of liver metastasis in NE cancers (Graphical abstract)." (PMID 40492591, 2025). "We hope our findings can shed light on the potential roles of several genes including GALNT9 in conferring risk for PTC in this population, thereby contributing to a better understanding of this prevalent cancer." (PMID 37686511, 2023). "Cancer cells with aberrant GALNT9 that reach the brain are perhaps favored to proliferate in the new microenvironment through dysregulated cell–cell interaction." (PMID 28993799, 2017). "However, the precise role of GALNT9 in cancer biology, particularly in PTC, remains under-explored and needs to be the focal point of future research to elucidate the potential role of GALNT9 in cancer susceptibility." (PMID 37686511, 2023). "By analyzing exome-sequencing data from 249 PTC patients (cases) and 1395 individuals without any known cancer (controls), GALNT9 emerged as being strongly associated with rare inactivating variants (RIVs) (4/249 cases vs. 1/1395 controls, OR = 22.75, p = 5.09 × 10−5)." (PMID 37686511, 2023). "In addition, ST8SIA3 and GALNT9 might have an inhibitive role in cancer promotion by negatively modulating the activity of DNA damage and the EMT, PI3K/AKT, and mTOR pathways." (PMID 37663248, 2023). "Our findings indicate that NE cancer cells mimic this pathophysiological process to trigger MBL signaling and complement activation via a distinct form of glycan, the GALNT9‐catalyzed O‐GalNAc." (PMID 40492591, 2025). "GALNT9 (an initiator of O-glycosylation) is a member of a sub family that differs significantly in the sequence from other GALNAC-T members, and has been shown to be dysregulated in cancer by promoter methylation." (PMID 36046250, 2022).
tumor (7 papers, 2014 to 2025). "GALNT9 expression is probably a marker for more mature stages of neuroblastic tumor cells, which are associated with less aggressivity." (PMID 24904828, 2014). "To ensure that CoBRA digests were representative of high methylation status in tumours, we carried out base-resolution analysis of promoter region methylation for BNC1, CCDC8 and GALNT9 by cloning and sequencing individual bisulfite-modified alleles from select tumours." (PMID 26052355, 2015). "When a tumor cohort from 122 NB patients was analyzed, GALNT9 expression was associated with high overall survival, independently of the standard risk-stratification covariates, and it was significantly associated with disease-free survival for patients currently classified as low risk." (PMID 24904828, 2014). "We also found that participants who reported more minutes of exercise during the six-month follow-up had lower levels of GALNT9 methylation at follow-up, which is a healthy pattern of methylation change for this tumor suppressor gene." (PMID 34439282, 2021). "BNC1, CCDC8 and GALNT9 were frequently downregulated or silenced in these tumours and reduced expression correlated to promoter methylation as determined by CoBRA and base-resolution sequencing." (PMID 26052355, 2015). "Particularly, GALNT9 expression was proposed as a marker for positive outcome in the low-risk NB subgroup, whereas lack of its expression had a predictive value for tumor relapses." (PMID 26309160, 2015). "Genes with reported anti-tumor functions, including SCGB1D2 (Secretoglobin Family 1D Member 2, lipophilin B), FKBP5, CD52, DLK1, GALNT9, GNG2, GDNF, and TMEM35A, were significantly upregulated after CUDC-907 + MPA treatment and validated by RT-PCR." (PMID 41262902, 2025). "NB patients displaying expression of GALNT9 in their tumor showed higher survival rates than patients with no expression." (PMID 26309160, 2015).
GALNT9 also shares sentences with these, for which no sentence is quoted: colorectal cancer (3 papers); cervical cancer (2); glioblastoma (2); serous ovarian cancer (2); adenoma (1); astrocytoma (1); colon Cancer (1); hepatocellular carcinoma (1); Papillary Thyroid Carcinoma (1); pituitary tumor (1); thymoma (1); thyroid cancer (1).